CHGA (chromogranin A)
Diseases named in the same sentence as CHGA in open-access papers (continued):
Sharing a sentence is not in itself a finding about the gene and the disease.
tumor (continued). "The first clear-cell pancreatic “sugar” tumor that exhibits abundant cytoplasmic glycogen is HMB-45 positive, and is also cytokeratin, NSE, and chromogranin A negative, similar to “sugar” tumors of the lung." (PMID 37251595, 2023). "Tumor markers in the blood, including S100B, CEA, CA-19–9, CA125, CA15-3, CA72-4, cyfra, synaptophysin, and chromogranin A, were not elevated." (PMID 35501497, 2023). "Immunohistochemical examination of these cells showed that the tumor cells were positive for synaptophysin and partially positive for CD56, and negative for chromogranin A and CAM5.2." (PMID 35235080, 2022). "F-PNET, Chromogranin A (CgA) ≥200pmol/L, high Ki67 index, G3-NEC, lymph node positivity, and tumor stage IV were significant negative predictors of OS." (PMID 35837305, 2022). "Immunohistochemical staining of the tumour was positive for Renin, CD34, Vimentin, and synaptophysin (Syn) and negative for somatostatin receptor 2 (SSTR2) and chromogranin A (CgA)." (PMID 35303838, 2022). "Thereafter, immunohistochemical staining revealed that the tumor cells were diffuse positive for synaptophysin and CD56 and negative for chromogranin A." (PMID 35653037, 2022). "GCA usually shows immunoreactivity for neuroendocrine markers, such as chromogranin A, synaptophysin, and CD56 in variable numbers of tumor cells, but these stains are not required for diagnosis." (PMID 34804955, 2021). "Immunohistochemical analyses revealed that the tumor cells were negative for CD56, chromogranin A, synaptophysin, and PSA." (PMID 34479548, 2021). "Immunohistochemically, tumor cells were negative for thyroid transcription factor-1 (TTF-1), negative for thyroglobulin, negative for chromogranin A (positive for normal parathyroid tissue within the nodule), positive for PTH, and positive for parafibromin." (PMID 33978837, 2021). "No specimen stained for Chromogranin A. Single cell positivity can be found in CD56-positive tumor infiltrating lymphocytes, but the strong positivity is considered relevant when the tumor cells themselves express CD56." (PMID 34449584, 2021). "In this case, tumor cells were eosinophilic on hematoxylin and eosin (HE) staining, negative for TTF-1, thyroglobulin, and chromogranin A, and positive for PTH on immunostaining." (PMID 33978837, 2021). "As immunohistochemical analyses showed the tumor cells to be negative for CD56, chromogranin A, synaptophysin, and PSA, the definitive diagnosis was ASCP." (PMID 34479548, 2021). "The immunohistochemical findings demonstrated that the tumor cells were positive for vimentin, CD34, and actin but negative for chromogranin A." (PMID 32441904, 2020). "The tumor cells were negative for CD117, DOG1, SMA, desmin, S-100, synaptophysin, and chromogranin A. On the basis of the histology and immunostaining profile, the tumor was diagnosed as a malignant SFT of the pancreas." (PMID 33188464, 2020). "Immunohistochemically, the tumor cells were positive for hepatocyte paraffin 1, AE1/AE3, and CD10 and negative for AFP, progesterone receptor, vimentin, chromogranin A, and synaptophysin." (PMID 31784920, 2019). "Immunohistochemical staining showed that the tumor cells were negative for AE1/AE3, CK18, CK7, CK19, Hepatocyte Paraffin-1, Glypican-3, Arginase-1, CD56, Chromogranin A, Synaptophysin, Vimentin, and Carcinoembryonic antigen." (PMID 31488173, 2019). "The tumor cells were positive for cytokeratin, nuclear/membranous β-catenin, CD10, and CD56 and were negative for chromogranin A, synaptophysin, progesterone receptor, vimentin, and Bcl-10." (PMID 31784920, 2019). "The tumor is negative for EMA, cytokeratin 7, cytokeratin 20, chromogranin A, synaptophysin, S-100 protein, HMB-45, desmin, SMA, EBV, CD117, DOG1, CD23, CD21, clusterin, MDM2, CD34, D240, and ERG." (PMID 31623602, 2019).
tumor (continued). "Because chromogranin A concentration correlates with the secretory activity of functioning tumors, a reduction of marker levels may occur during treatment with antiproliferative somatostatin analogue reflecting the inhibition of the secretory activity of the tumor rather than an antitumor effect." (PMID 30057604, 2018). "The tumor cells were negative for synaptophysin, SMA (smooth muscle actin), TTF-1 (thyroid transcription factor-1), Chromogranin A, desmin, GFAP, WT-1 (Wilm’s tumor gene-1), HBME-1 (Hector Battifora mesothelial epitope-1)." (PMID 30285886, 2018). "The tumor cells were negative for CK20, synaptophysin, chromogranin A, transthyretin, TTF-1, RCC, thyroglobulin, and CD10." (PMID 30340515, 2018). "Immunostaines for RCC, CD10, CK20, chromogranin A, synaptophysin, TTF-1, thyroglobulin, and transthyretin were negative in the tumor cells." (PMID 30340515, 2018). "Tumor cells were positive for vimentine and EMA, and were negative for SMA, TTF-1, Chromogranin A, synaptophysin." (PMID 30285886, 2018). "The tumor cells were positive for synaptophysin and weakly positive for NCAM, but negative for chromogranin A. Epithelial markers (AE1/AE3 and CAM5.2) accentuated intracytoplasmic globules." (PMID 29938394, 2018). "Immunohistochemically, tumor cells were positive for cytokeratin (CK)-AE1/3, CK7, TTF-1, CEA, calcitonin, synaptophysin, and chromogranin A, but negative for CK20, Napsin A, Pax8, and p40." (PMID 29237502, 2017). "Examination of the tumor showed medium-sized tumor cells that were positive for CD56 and chromogranin A, with no necrosis, and with a mitotic count less than 1/10 HPF." (PMID 27840746, 2016). "The tumor was positive for AE1/AE3 and negative for CD3, CD56, CD79a, synaptophysin, and chromogranin A expression." (PMID 27818885, 2016). "Histologic examination revealed small, round to oval tumor cells arranged in cords or nests, containing hyperchromatic nuclei and mitotic figures; the tumor was positive for synaptophysin and CD56 and negative for chromogranin A expression." (PMID 27818885, 2016). "In the present case, the medium-size tumor cells were positive for CD56 and chromogranin A, had no necrosis, and had a mitotic count less than 1/10 HPF." (PMID 27840746, 2016). "In this case, the tumor cells were proven chromophobic by Pearse’s PAS stain, showing immunopositivity for PRL, chromogranin-A, and synaptophysin but no immunoreactivity to S-100 protein, vimentin, and GFAP." (PMID 26228535, 2015). "The tumor tissues contain nerve fibers with and without medullary sheaths, and immunohistochemical analysis reveals positive staining for NF, NSE, Syn and chromogranin A." (PMID 25013498, 2014). "Immunohistochemically, the tumor cells were positive for synaptophysin and CD56 and negative for chromogranin A. Only a few tumor cells were positive Ki-67." (PMID 25392779, 2014). "The tumor cells were negative for CK20 and EMA, as well as for HCC marker, RCC marker, TTF-1, ER, PR, CA-125, and chromogranin A." (PMID 24955270, 2014). "On immunohistochemistry, the tumor cells are typically negative for epithelial markers (i.e., EMA and cytokeratins), chromogranin A, synaptophysin, S-100, HMB45, and Melan-A." (PMID 25587475, 2014). "Immunohistochemical staining showed that the tumor cells were strongly positive for vimentin and CD99, focally positive for neuron specific enolase (NSE) and chromogranin A (CgA), and negative for cytokeratins, CD3, desmin, and leukocyte common antigen (LCA)." (PMID 23537038, 2013). "Immunohistochemically, the tumor was positive for CD99, vimentin, neuron specific enolase and chromogranin A, and negative for cytokeratins, CD3, desmin, and leukocyte common antigen." (PMID 23537038, 2013).
tumor (continued). "While CT and MRI remain the primary modalities for post-treatment follow-up, especially in high-grade or disseminated disease, tumor markers such as CEA, CA19-9, and occasionally chromogranin A may be useful for monitoring, although no marker is specific." (PMID 40724549, 2025). "Immunohistochemical markers such as neuronal specific enolase, synaptophysin, chromogranin A and CD56 are not always positive in GCAs, and tumours with absent neuroendocrine immunoreactivity may exist." (PMID 40729214, 2024). "In vivo, although reduction of CELSR3 did not impact NEPC tumor growth rate or metastatic potential, we did find that reduction of CELSR3 resulted in a diminution of NEPC markers (e.g., SYP, ASCL1, INSM1, SYP, and CHGA) in vitro and in vivo." (PMID 37546702, 2023). "Evaluation of both NSE and CHGA concentration increases the reliability of NEN diagnosis; however, given the non-specific nature of these markers, they do not provide information on the primary tumor site and its origin." (PMID 32537434, 2020). "Tumor-derived NE-like cells are localized in tumor foci and are non-proliferating, terminally differentiated cells rich in serotonin and positive for NE markers, including neuron-specific enolase (NSE) and chromogranin A (CGA)." (PMID 29892571, 2018). "Immunohistochemically, the tumor was strongly positive for keratin 7 (CK7) and pankeratin AE1/AE3, and alpha 1 antichymotrypsin; negative for synaptophysin and chromogranin A, CDx2, CK20, S100, carcinoembryonic antigen (CEA), MUC 2, MUC5AC, and somatostatin; and in part positive for CA19-9." (PMID 29145864, 2017). "The tumor cells were positive for CD56 and chromogranin A, negative for HMB-45." (PMID 22741527, 2012). "The tumor cells were positive for CD99 and negative for chromogranin A, keratin and desmin." (PMID 21494688, 2011). "Immunohistochemical staining showed that the tumor cells were negative for AE1/AE3, CK18, CK7, Hepatocyte Paraffin-1(Hep Par-1), Glypican-3 (GPC-3), Arginase-1 (ARG-1), CD56, Chromogranin A (CgA), Synaptophysin (Syn), Vimentin, and Carcinoembryonic antigen (CEA)." (PMID 31488173, 2019).
cancer (69 papers, 1996 to 2026). A tumor composed of atypical neoplastic, often pleomorphic cells that invade other tissues. "Here, we identify a sub-set of chromogranin A-positive enteroendocrine cells that are positive for the developmental and cancer-associated transcription factor Brachyury in normal human small intestinal and colonic crypts." (PMID 26862851, 2016). "Lower levels of GAST (gastrin) RNA in cancer tissues could help explain the concomitant loss of the gastrin signaling factor CHGA (chromogranin)." (PMID 22929309, 2012). "We investigated 92 putative cancer‐related plasma proteins including chromogranin A (CgA) and clinical parameters at the time of diagnosis to identify early factors associated with progressive (PD) or stable disease (SD)." (PMID 40812788, 2025). "Negativity for Chromogranin A and Synaptophysin excluded carcinoma subtypes with neuroendocrine differentiation as described for both species (Data not shown)." (PMID 39696035, 2024). "Generally, this NE phenotype is positive for markers of other high-grade NE carcinomas, such as chromogranin A(CHGA), neuron-specific enolase (NSE), synaptophysin (SYP), and CD56, and negative for luminal prostate differentiation markers." (PMID 37455903, 2023). "qPCR analysis showed high levels of ChgA, Bmi1, and glycolytic gene expression in Pdk1-mCherry+ cells compared to Pdk1-mCherry−, indicating that pPDH+ cancer cells exhibit the same cell phenotype than pPDH+ cells in the normal epithelium." (PMID 35314684, 2022). "For the original sample, NE marker expression was limited to approximately 10% of the cancer cells and <5% of the benign ductal epithelium that demonstrated cytoplasmic positivity for chromogranin A stain." (PMID 36643868, 2022). "Tissue diagnosis require haematoxylin and eosin stains to demonstrate the neuroendocrine phenotype along with immune histochemistry for synaptophysin and chromogranin-A and for carcinoma markers." (PMID 36078951, 2022). "These cancers have positive immunohistochemical neuroendocrine markers which include synaptophysin, chromogranin A, CD56, and/or NSE." (PMID 31752927, 2019). "It is increasingly clear that inflammatory diseases and cancers are influenced by cleavage products of the pro-hormone chromogranin A (CgA), such as the 21-amino acids long catestatin (CST)." (PMID 30337922, 2018). "Chromogranin A (CgA), a neuroendocrine secretory protein, and its fragments are present in variable amounts in the blood of normal subjects and cancer patients." (PMID 27683038, 2016). "The microscopic examination revealed that the mass was composed of a monotonous population of small cells and that the cells of the carcinoma were positive for cluster of differentiation 56, chromogranin A and synaptophysin." (PMID 24520292, 2014). "Cancer cells stained positive for both synaptophysin and chromogranin A (individual reactivity rate 100%)." (PMID 23734899, 2013). "While the presence of chromogranin A and synaptophysin expression suggests NED, it does not necessarily mean NEPC; immunohistochemical analysis of metastatic hormone-sensitive prostate cancer reveals that 61% of primary cancer specimens are positive for chromogranin A." (PMID 38962044, 2024). "CHGA was found in a series of cancers, and predicted poor outcome." (PMID 35549979, 2022). "The novel identification of a sub-class of ChgA-positive, Brachyury-positive EECs in adult, normal intestinal crypts and CRC cells provides an intriguing platform for further studies associated with normal homeostasis and cancer biology." (PMID 26862851, 2016).
cancer (continued). "Chromogranin A, a neuroendocrine marker, might be elevated if there is a neuroendocrine differentiation of the carcinoma." (PMID 24885487, 2014). "In this context, it is of note that two of the four carcinomas with neuroendocrine differentiation in the present study only expressed chromogranin A or synaptophysin and not both of these markers, arguing for a routine immunohistochemical panel including both chromogranin A and synaptophysin." (PMID 24701575, 2014). "Knockdown of CHGA and UCHL1 significantly regulate cancer behaviours of HCT‐116, including inhibition of cell migration, invasiveness, cell cycle G1/S arrest and reactive oxygen species (ROS) generation." (PMID 37246623, 2023). "Altogether, the identification of UCH‐L1 and CHGA, as the novel biomarkers and the new molecular targets of LNM respective for the early prognosis and treatment of cancer growth, migration and invasion in CRC." (PMID 37246623, 2023). "HSP prevented BON cancer cell proliferation and induced cancer cell death by decreasing achaete-scute complex-like 1(ASCL1), chromogranin A (CgA), and enhanced Notch 1 expression." (PMID 35128104, 2022). "Three of these proteins—CCL15, CHGA, and KLK10— are known to be prognostic markers for various types of cancer, and upregulation of these proteins is correlated with poorer prognosis." (PMID 36613555, 2022). "We found that the cancer subtype markers (GRP, CHGB, NEUROD1, and CHGA for NET; KRT5, DSC3, KRT6B, TP63, and KRT6A for SCC; and NKX2-1, KRT7, NAPSA, and MUC1 for ADC) were specifically expressed in the corresponding cancer subtypes." (PMID 35962452, 2022). "In this review, we focus on how full‐length chromogranin A and its peptides, including PST, vasostatin‐1, CST, and serpinin, as important modulators of cardiovascular functions, immunometabolism, and cancer." (PMID 31588572, 2019). "Chromogranin A, synaptophysin, S-100B protein and GFAP are well known neuroendocrine markers involved in cancer and in neurological diseases." (PMID 31263455, 2019). "Chromogranin-A did not differentiate between cancer CTT tissue or normal resident neuroendocrine cells." (PMID 40141825, 2025). "The CHGA protein was positively expressed in the normal colon and adjacent colon mucosa (the brown colour) and lost the CHGA expression in the CRC regardless of well, moderate, or poor differentiation of the cancers." (PMID 35681650, 2022). "Importantly, routinely used diagnostic markers such as chromogranin A or synaptophysin were not among the highly enriched markers in our proteomics analysis and may thus fail to identify the neuroendocrine differentiation of these cancers." (PMID 36443295, 2022). "In addition, some cancer cells were positive for CD56, chromogranin A, and synaptophysin, indicating focal NED." (PMID 31281709, 2019). "Immunohistochemically, the adenocarcinoma cells were negative for chromogranin A and synaptophysin, whereas the round-shaped carcinoma cells were diffusely positive for synaptophysin but negative for chromogranin A and p40." (PMID 29740725, 2018). "Three out of five of the cancers studied were Brachyury-positive but ChgA-negative (data not shown)." (PMID 26862851, 2016). "Immunohistochemically, these carcinoma cells were negative for all three neuroendocrine markers, i.e., synaptophysin, chromogranin A and CD56, TTF-1, CEA, CK20, h-caldesmon, α-SMA, calponin, and CD10, but specifically positive for 34βE12, CK7 and p63." (PMID 23231806, 2012). "When the density of NE cancer cells was recorded, a progressive and significant increase in expression from non-neoplastic prostate glands (0.4% mean of Chromogranin A positive cells) to primary tumors (1.0%) and lymph node metastases (2.6%; p < 0.001) was noted for Chromogranin A." (PMID 28788048, 2017). "Biopsy and immunohistochemical findings including negative Synaptophysin and Chromogranin A staining and positive Trypsin and BCL10 staining suggested a carcinoma with acinar cell differentiation." (PMID 38625458, 2024).
cancer (continued). "Among the NE markers, synaptophysin was variably positive in two NUT carcinomas (2/6, 33%); however, all cases were negative for ASCL1, chromogranin A, and CD56." (PMID 38326851, 2024). "Undifferentiated carcinoma was confirmed based on the presence of small round atypical cells with the formation of a solid alveolar lesion on histopathological examination and immunohistochemical staining that was positive for CAM 5.2 but negative for chromogranin A and synaptophysin." (PMID 28063144, 2017).